RHOB (ras homolog family member B)
Diseases named in the same sentence as RHOB in open-access papers (continued):
Sharing a sentence is not in itself a finding about the gene and the disease.
melanoma (9 papers, 2009 to 2025). A malignant, usually aggressive tumor composed of atypical, neoplastic melanocytes. "Further, they revealed that loss of RhoB expression in metastatic melanoma tissues is correlated with an increase in progression-free survival of BRAF-mutant patients that were treated with vemurafenib." (PMID 29385717, 2018). "We therefore examined the impact of PLX4032 and MEKi on RHOB expression in wild type BRAF melanoma cells harboring mutations in NRAS (WM1346 and SK-MEL2 cells), KIT (WM3211 cells) or KRAS (WM1791C cells)." (PMID 26098773, 2015). "Herein, we show that BRAFV600 mutant causes a MAPK-dependent decrease of RHOB expression in melanoma cell lines." (PMID 26098773, 2015). "Following BRAF inhibition, RHOB activates AKT whose inhibition causes hypersensitivity of BRAF-mutant melanoma cells to BRAF inhibitors." (PMID 26098773, 2015). "Next, we ectopically expressed the mCherry-tagged endosomal marker RhoB (mCherry-Endo-14) in A375 melanoma cells." (PMID 32531927, 2020). "Overall these data show that RHOB depletion triggers caspase-dependent apoptosis of BRAF-mutant melanoma cells exposed to MAPK inhibitors." (PMID 26098773, 2015). "In this study we demonstrate that inhibition of mutant BRAF in melanoma cells with pharmacological inhibitors or siRNA knockdown results in the activation of the c-Jun/RHOB/AKT signaling axis, which leads to cell survival." (PMID 26098773, 2015). "Using RT-qPCR screening, we detected a significant induction of RHOB expression upon PLX4032 treatment in BRAF-mutant melanoma cells." (PMID 26098773, 2015). "PLX4032 treatment also increased RHOB protein level in six other BRAF-mutant melanoma cell lines, which are representative of melanoma progression (RGP-VGP to metastatic)." (PMID 26098773, 2015). "We conclude that PLX4032 triggers a sustained induction of RHOB expression in BRAF-mutant melanoma cells." (PMID 26098773, 2015). "Wnt5a was able to polarise the cellular cytoskeleton of melanoma cells through a process dependent on dishevelled, RhoB and Rab4 to promote cellular migration towards the source of the CXCL12 chemokine." (PMID 22655072, 2012). "RhoB expression was reduced in melanoma cells when compared to primary human melanocytes." (PMID 29385717, 2018). "QPCR results indicated that the expression of RhoA, RhoB and RhoC reduced in melanoma cells." (PMID 28404912, 2017). "Given that RHOB depletion determines the cellular response to PLX4032 in BRAF-mutant melanoma cells, we hypothesized that the basal expression of RHOB may predict the response to BRAFi." (PMID 26098773, 2015). "Next we addressed whether RHOB induction by PLX4032 in BRAF-mutant melanoma cells was related to BRAF inactivation." (PMID 26098773, 2015). "Finally, we demonstrate that the expression of RHOB in melanoma tissues determines a poor clinical response to PLX4032." (PMID 26098773, 2015). "C-Jun, a key component of the AP-1 complex, induces the expression of RHOB and activates the AKT signaling pathway, promoting the survival of melanoma cells under BRAFi stress." (PMID 41198656, 2025). "Mechanistic studies revealed that RhoB modulates the response of melanoma cells in vitro to PLX4032, a different BRAF kinase inhibitor, via the AKT pathway and combination of an AKT inhibitor with PLX4032 in vivo reversed RhoB-mediated resistance to PLX4032." (PMID 29385717, 2018). "We used a siRNA strategy to reduce RhoA, RhoB, or RhoC expression in CD70+ LB1319-MEL human melanoma cells." (PMID 26828592, 2016). "Here, we show that, in BRAF-mutant melanoma cells, inhibition of BRAF or its target MEK induces RHOB expression by a mechanism that depends on the transcription factor c-Jun." (PMID 26098773, 2015). "Altogether, these findings support a potential role for RHOB as a predictive biomarker to PLX4032 therapy and the c-Jun/RHOB/AKT signaling axis as a new target to prevent resistance to BRAFi of BRAF-mutant melanoma tumors." (PMID 26098773, 2015).
melanoma (continued). "Here, we show that in BRAF-mutant melanoma cells, PLX4032 induces c-Jun activation resulting in RHOB expression and subsequent AKT activation." (PMID 26098773, 2015). "Our findings reveal that BRAF inhibition activates a c-Jun/RHOB/AKT pathway that promotes tumor cell survival and further support a role of this pathway in the resistance of melanoma to vemurafenib." (PMID 26098773, 2015). "Intravenous injection of B16-F10 melanoma cells overexpressing RhoB, but not RhoA, inhibited colonization of melanoma cells in the lung in their mouse model." (PMID 29385717, 2018). "The observation of a persistent RHOB expression after PLX4032 removal, despite ERK re-phosphorylation, suggests that RHOB participates to an original long lasting adaptive cellular program in melanoma cells." (PMID 26098773, 2015). "Cell lines with low RHOB expression were more sensitive to PLX4032, suggesting that, in melanoma cells, high RHOB expression may predict a poor response of BRAF-mutant patients to PLX4032." (PMID 26098773, 2015). "Efficient inhibition of MAPK signaling with PLX4032 or AZD6244, demonstrated by inhibition of ERK phosphorylation, did not significantly affect RHOB expression even with a higher dose (5 μM) than that used in melanoma cells (1 μM)." (PMID 26098773, 2015). "According to our cellular data, the patient's samples revealed an absence of RHOB expression in more than 70% of melanoma tissues bearing BRAFV600E mutants." (PMID 26098773, 2015). "Both Wnt1 and Wnt3a have been shown to activate RhoA, whereas the non-canonical Wnt5a promotes melanoma migration via RhoB." (PMID 19473496, 2009). "Treatment of B16-F10 melanoma cells with LY294002, a PI3K inhibitor, strikingly induced RhoB, but not RhoA protein levels." (PMID 29385717, 2018).
pancreatic cancer (9 papers, 2002 to 2025). "In conclusion, this study indicates that the hsa-miR-3178/RhoB/PI3K/Akt-mediated upregulation of ABC transporters play a vital role in inducing gemcitabine resistance in pancreatic cancer cells." (PMID 35538494, 2022). "Through literature investigation, we found that RhoB plays a biological function as a cancer promoter in pancreatic cancer." (PMID 35538494, 2022). "In this study, we propose that hsa-miR-3178 inhibits RhoB to promote gemcitabine resistance in pancreatic cancer via activating PI3K/Akt signaling pathway and upregulating ABC transporters." (PMID 35538494, 2022). "For example, Sp1-driven up-regulation of miR-19a decreases RHOB and promotes pancreatic cancer cell proliferation, migration and invasion." (PMID 28422727, 2017). "Recent reports also demonstrated that Sp1 promotes other miRNA gene expression such as miR-19a, and Sp1 was also regarded as an upstream factor of miR-19a mediated down-regulation of RHOB and promotion of pancreatic cancer." (PMID 29340098, 2017). "Our study has demonstrated that RHOB is down-regulated in human pancreatic cancers and suppresses progression of pancreatic cancer by inhibiting proliferation, migration and invasion, as well as by inducing apoptosis." (PMID 26041879, 2015). "In pancreatic cancer, the relationship between RhoB and gemcitabine resistance remain elusive." (PMID 35538494, 2022). "Levels of RHOB expression were detected in pancreatic cancer tissues of 12 patients." (PMID 26041879, 2015). "Importantly, the promoting effect of miR-19a on pancreatic cancer progression depends on inhibition of RHOB." (PMID 26041879, 2015). "Furthermore, RHOB levels were inversely correlated with miR-19a levels both in pancreatic cancer tissues and in adjacent tissues." (PMID 26041879, 2015). "Furthermore, RHOB was down-regulated in human pancreatic cancer samples." (PMID 26041879, 2015). "A recent study has shown that the inhibition of RHOB by hsa-miR-3178 can increase the expression of ABC transporter proteins through the PI3K/Akt pathway, which finally leads to the resistance of pancreatic cancer to gemcitabine." (PMID 40574864, 2025). "RHOB is a tumor suppressor gene in many type of cancers, however, RHOB, not like PTEN, is known much less in pancreatic cancer." (PMID 26041879, 2015).
cervical carcinoma (8 papers, 2011 to 2025). A carcinoma arising from either the exocervical squamous epithelium or the endocervical glandular epithelium. "Here, we report that RhoB is activated in human breast and cervical cancer cell lines shortly after treatment with agents that cause DNA damage." (PMID 21373644, 2011). "RhoB can inhibit the activity of the cyclin B1 promoter to reduce its expression level, which in turn leads to cervical cancer cell death." (PMID 40655948, 2025). "In cisplatin-resistant prostate and cervical cancer cells, lovastatin overcomes resistance by upregulating tumor suppressor genes such as Ras homolog family member B (RHOB) and kruppel-like factor 2 (KLF2) and 6 (KLF6)." (PMID 34065757, 2021). "Here, we show that RhoB activity increases in human breast and cervical cancer cell lines after treatment with DNA damaging agents." (PMID 21373644, 2011). "The microarray dataset of mRNA and miRNA analysis revealed RhoB and STMN1 genes as potential targets for cervical cancer diagnosis and treatment." (PMID 33946372, 2021). "Interestingly, the LIR motif is also present in both the RhoA and RhoB proteins, and their levels were modestly increased by RAB33A overexpression in cervical cancer cells." (PMID 40000633, 2025).
colon carcinoma (8 papers, 2013 to 2025). "In human colon epithelial cells, it was reported that miR-223 targeting of RHOB limited the spread of colon cancer cells." (PMID 36231106, 2022). "In a previous study, aloe emodin inhibited colon cancer cell migration/angiogenesis by downregulating MMP-2/9, RhoB, and VEGF." (PMID 36212129, 2022). "For example, constitutive expression of active RhoB in HCA-7 and LS-174 colon carcinoma cells led to increased levels of COX-2." (PMID 26416248, 2015). "The results showed that C17orf57 and SEMA4B were positively correlated with MSI, while RHOB presented a negative correlation in colon cancer." (PMID 40574864, 2025). "In line with this, we did not detect active RhoB in control or AZA197 treated colon cancer cells, consistent with the general aggressive behavior of these cells (data not shown)." (PMID 24279335, 2013).
prostate carcinoma (8 papers, 2012 to 2024). A carcinoma that arises from epithelial cells of the prostate gland. "This is highlighted by our findings showing that low RHOB expression is significantly associated with prostate cancer and clinical markers of disease progression." (PMID 36831632, 2023). "RhoB has also been linked to hypoxia and has been validated as a target of miR-21 in various cell types, but no study to date has explored the link between miR-21 and RHOB expression in prostate cancer." (PMID 36831632, 2023). "In prostate cancer, the overexpression of RhoB increased cell activity and increased migration ability, suggesting that RhoB has a cancer-promoting effect, which is consistent with our results." (PMID 39336777, 2024). "This study presents evidence that hypoxia is a key contributor to the over-expression of miR-21 in prostate tumours, which can subsequently promote prostate cancer progression by suppressing RHOB expression." (PMID 36831632, 2023). "We demonstrate that miR-21 up-regulation can alter the behaviour of normal prostate cells and we further show for the first time in prostate cancer that it down-regulates RHOB, a tumour suppressor gene." (PMID 36831632, 2023). "This is the first study to show that the hypoxia-induced expression of miR-21 in prostate cells can promote prostate cancer progression by down-regulating the tumour suppressor gene RHOB." (PMID 36831632, 2023). "RHOB codes for the tumour suppressor RhoB and has been validated as a target of miR-21 in breast, colorectal and cervical cancer cells, but this is the first study to link miR-21 and RHOB in prostate cancer." (PMID 36831632, 2023). "In vitro and in silico analyses demonstrated that miR-21 down-regulates the tumour suppressor gene Ras Homolog Family Member B (RHOB) in prostate cancer." (PMID 36831632, 2023). "This is the first report to present research showing how the hypoxia-induced up-regulation of miR-21 can contribute to prostate cancer development through its regulation of RHOB." (PMID 36831632, 2023). "The results presented here show that RhoB can affect levels and localization of cadherins in prostate cancer cells, thus participating in the maintenance of epithelial integrity." (PMID 25630770, 2015). "Our work extends the types of membrane receptors regulated by RhoB to include cadherins and indicates a mechanism by which RhoB downregulation can contribute to tumor progression in prostate cancer." (PMID 25630770, 2015). "Here we describe a new function for RhoB in maintaining cell-cell junctions in epithelial DU145 prostate cancer cells by regulating E-cadherin expression and localization." (PMID 25630770, 2015). "It has been shown that diminishing RhoB expression in different cell models causes reduction in the amount of integrins available on the cell surface, namely β1 in prostate cancer cell line and β2 and β3 in macrophages derived from RhoB−/− mice." (PMID 24466204, 2014). "This RHOB expression profiling consistently showed the opposite trend to that observed for miR-21, implying that it is targeted by miR-21 in prostate cancer." (PMID 36831632, 2023). "Although in vivo experiments involving the over-expression and/or knockdown of either molecule in mice were beyond the scope of this study, this would be a sensible approach in any future work looking to unravel the biological mechanisms that link miR-21 and RhoB in prostate cancer." (PMID 36831632, 2023). "Taken as a whole, these data indicate that the down-regulation of RhoB by miR-21 could have implications for both prostate cancer cell function and the regulation of the tumour microenvironment as a whole." (PMID 36831632, 2023). "However, this is the first report to implicate RhoB in the cellular response to hypoxia in prostate cancer." (PMID 36831632, 2023). "Indeed, the depletion of RhoB in prostate cancer cells has been shown to reduce cell–cell adhesion, inhibit apoptosis and increase cell migration." (PMID 36831632, 2023).
prostate carcinoma (continued). "In addition, RhoB influenced the expression of the matrix metalloproteinases (MMPs) in prostate cancer DU145 and promoted DU145 cell motility and invasion." (PMID 28042950, 2017). "Among the genes uniquely activated by TC-AR is RHOB which is shown to be involved in the increased migration and morphological changes observed in LN/TC-AR, suggesting a role of RHOB in the regulation of androgen-independent behavior of prostate cancer cells." (PMID 23209612, 2012). "We have previously shown that RhoB depletion alters focal adhesion dynamics and reduces surface levels of β1 integrin in PC3 prostate cancer cells, correlating with increased migration speed." (PMID 25630770, 2015). "Here we show that RhoB depletion reduces cell-cell adhesion and downregulates E-cadherin levels as well as increasing internalized E-cadherin in DU145 prostate cancer cells." (PMID 25630770, 2015). "We also show that RhoB controls the levels of N-cadherin the mesenchymal-like PC3 prostate cancer cell line, which does not express E-cadherin." (PMID 25630770, 2015). "RhoB expression is reduced in several tumor types, including some prostate carcinomas, compared to non-cancer tissues and it is targeted by the miRNA miR21, involved in cancer progression." (PMID 25630770, 2015). "Using the Cancer Genome Atlas (TCGA) dataset, we observed that high expression of CTBP2 was significantly correlated with poor overall survival of prostate cancer patients, while AKAP12, HIF1A and RHOB were not." (PMID 38698344, 2024). "On the other hand, mouse macrophages lacking RhoB, or human PC3 prostate cancer cells depleted of RhoB by RNAi, migrate faster than control cells." (PMID 25630770, 2015).
glioma (7 papers, 2014 to 2021). A benign or malignant brain and spinal cord tumor that arises from glial cells (astrocytes, oligodendrocytes, ependymal cells). "Sylvie M also reported that ανβ3 and ανβ5 regulate mitotic cell death via ILK (integrin-linked kinase) and RhoB signaling pathways, which participate in the radioresistance of glioma cells." (PMID 23755149, 2014). "Among these, only RHOB has been firmly linked to high-grade glioma albeit with contrasting results." (PMID 26132659, 2015). "Glioma-associated DEGs DOCK6, ILK, MGMT, NOTCH4 were up-regulated and FGF10, JAK1, JUNB, RHOB were down-regulated uniquely in the mouse." (PMID 29352201, 2018). "In glioma, miR-19a negatively regulates the expression of tumor suppressor proteins RhoB and RUNX3." (PMID 32906592, 2020). "Seven Rho GTPases (RND1, RND3, RAC3, RHOA, RAC2, RAC1 and RHOC) showed a significantly greater connectivity in grade IV glioma and seven (CHP, RHOD, RHOF, RHOB, RHOQ, RND2, RHOBTB3) showed greater connectivity in grade II glioma." (PMID 26132659, 2015). "Other genes uniquely altered in mouse gliomas (e.g. NOTCH4, FGF10, JUNB, RHOB) may contribute further to murine-specific differences in glioma biology." (PMID 29352201, 2018).
lung adenocarcinoma (6 papers, 2015 to 2024). A carcinoma that arises from the lung and is characterized by the presence of malignant glandular epithelial cells. "Conversely, one study identified a role for RHOB in promotion of metastases in lung adenocarcinoma in a murine model evaluated bony metastasis." (PMID 31200451, 2019). "More recently, we have revealed that RHOB knock-out is critical to determine tumor aggressiveness in a murine EGFRL858R-induced lung adenocarcinoma." (PMID 26098773, 2015). "In lung adenocarcinoma (LUAD), the miR-21-5p/Ras Homolog Family Member B (RhoB) axis plays a crucial role in regulating epithelial-mesenchymal transition (EMT)." (PMID 39512697, 2024). "Knockdown of RhoB significantly decreased cell viability during treatment of PTX, indicating that RhoB enhances cell resistance to PTX‐chemotherapy in lung adenocarcinoma cells." (PMID 26915688, 2016).
bladder cancer (5 papers, 2019 to 2025). "With the exception of RHOB, whose expression profile requires further clarification, the differential expression of the remaining proteins between bladder cancer and normal tissues was consistent with our analytical results." (PMID 40574864, 2025). "RhoB plays an important role in the effect of MVA pathway inhibition on the migratory capacity of bladder cancer cells and its protein stability is closely related to GGPP-mediated geranylgeranyl modification." (PMID 39521858, 2024). "It promoted invasion and epithelial to mesenchymal transition of bladder cancer cells by targeting RhoB." (PMID 32209726, 2020). "To investigate the protein expression profiles of six genes (ABCA7, HOOK2, JUNB, RHOB, VMP1, and ACTG1) that significantly impact both DSS and PFI in bladder cancer patients, we conducted Western blot analyses using SV-HUC-1 and 5637 cell lines." (PMID 40574864, 2025).